SOWAHC (sosondowah ankyrin repeat domain family member C)
Synonyms: ANKRD57; C2orf26; FLJ21870
Tractability: PROTAC: ubiquitination databases record sites on it; its protein half-life has been measured.
Gene: Protein-coding gene on chromosome 2 (109,614,364 to 109,618,990, forward strand). Ensembl gene ENSG00000198142.
Subcellular location (Human Protein Atlas): Cytosol
Pathways (Reactome):
Signal Transduction: RHOA GTPase cycle; RHOB GTPase cycle; RHOF GTPase cycle
Genetic constraint (gnomAD): Loss-of-function variants: 12 observed, 14.09 expected, observed/expected ratio (o/e) 0.85, 90% interval 0.55 to 1.38. The synonymous counts are far from expectation, so gnomAD's model fits this gene poorly and the ratio says little. Missense variants: 712 observed, 620.82 expected, observed/expected ratio (o/e) 1.15, 90% interval 1.08 to 1.22. Synonymous variants: 371 observed, 286.12 expected, observed/expected ratio (o/e) 1.3, 90% interval 1.19 to 1.41.
Homologues: Orthologues: chimpanzee SOWAHC (98% identical), macaque SOWAHC (95% identical), rat Sowahc (73% identical), mouse Sowahc (71% identical), rabbit SOWAHC (69% identical), zebrafish sowahca (35% identical), zebrafish sowahcb (33% identical). Paralogues in human: SOWAHB (26% identical), SOWAHA (22% identical), SOWAHD (15% identical).
Diseases named in the same sentence as SOWAHC in open-access papers:
SOWAHC is named in the same sentence as 3 diseases in open-access papers, as found by Europe PMC text mining. Sharing a sentence is not in itself a finding about the gene and the disease. The quoted sentences say what the papers report.
lung squamous cell cancer (2 papers, 2021 to 2022). "SOWAHC, encoding Ankyrin repeat domain-containing protein SOWAHC, is demonstrated to be prognostic in bladder cancer and lung squamous cell carcinoma." (PMID 33485349, 2021). "SOWAHC is a potential prognostic biomarker for lung squamous cell cancer." (PMID 35979430, 2022).
SOWAHC also shares sentences with these, for which no sentence is quoted: bladder cancer (1 paper); schizophrenia (1).